VIM (vimentin)
Diseases named in the same sentence as VIM in open-access papers (continued):
Sharing a sentence is not in itself a finding about the gene and the disease.
cancer (continued). "Natural human monoclonal antibodies obtained from sentinel lymph nodes of cancer patients identify cell surface vimentin." (PMID 40051499, 2025). "As a result, most of the metastatic lesions were more mesenchymal than each primary lesion in terms of a higher rate of vimentin-positive cancer cells." (PMID 40454484, 2025). "A sentinel LN processed vimentin to generate an antibody response which, in turn, recognizes a form of vimentin located on the cell surface of cancer cells." (PMID 40051499, 2025). "CDH1 and VIM protein levels changed similarly, and CD44s protein levels, overexpressed in cancer stem cells and during EMT, were partially depleted upon DOX stimulation indicating MET." (PMID 39759848, 2025). "Upregulation of CHD1L in cancer cells correlates with increased vimentin and slug expression, along with decreased E-cadherin, suggesting a shift toward EMT." (PMID 40442742, 2025). "Vimentin also plays a direct role in cancer cells, as demonstrated by the observation of reduced cell motility in cancer cells upon vimentin knockdown." (PMID 39780187, 2025). "The cancer-associated fibroblast (CAF)-enriched subtype showed elevated FAP and Vimentin expression, abundant CAFs, high proliferative activity, and poor prognosis." (PMID 40670349, 2025). "Conversely, CHD1L knockdown upregulates E-cadherin and suppresses vimentin and N-cadherin, indicating EMT reversal and loss of cancer stem cell traits." (PMID 40442742, 2025). "Numerous studies have underscored Snail-1’s impact on EMT-associated molecules, including E-cadherin, vimentin, MMP-9, and microRNAs like miR-34a, shaping cancer cells’ invasive, migratory, and metastatic potential." (PMID 40575155, 2025). "This PRMT1‐vimentin R64 asymmetric demethylation (aDMA) axis drives cytoskeletal reorganization and cancer cell migratory capacity, with functional validation in xenograft models demonstrating its critical requirement for metastatic colonization." (PMID 40884268, 2025). "Beyond wound healing, vimentin-positive EVs also open avenues for targeting EMT in cancer progression and metastasis." (PMID 40618999, 2025). "E-cadherin and vimentin (EMT markers): MALAT1 expression demonstrated a negative correlation with E-cadherin and a positive correlation with vimentin (p < 0.001), consistent across all cancer types." (PMID 40674376, 2025). "This is often characterized by a decrease in epithelial cell markers like E-cadherin and an increase in mesenchymal markers such as Vimentin and N-cadherin, indicative of enhanced migratory and invasive capabilities in cancer cells." (PMID 41019043, 2025). "To further validate the presence and activation of cancer-associated fibroblasts, we examined the expression of the CAF markers α-SMA and vimentin." (PMID 40677704, 2025). "Remarkably, endothelial cells directly suppress cancer cell mesenchymal properties, as evidenced by a 4.6 fold reduction in Vimentin expression compared to mono‐cultures." (PMID 40223399, 2025). "This study reveals that vimentin affects the miR‐615‐3p‐PICK1 axis through APA, revealing the key role of VIM in cancer progression." (PMID 39781570, 2025). "TGF‐β promotes EMT in cancer by regulating E‐cadherin, N‐cadherin, Snail, and vimentin transcriptional factors." (PMID 40584407, 2025). "EMT increases cancer invasiveness and metastasis by upregulating mesenchymal markers, including vimentin and N‐cadherin, and downregulating epithelial markers, such as E‐cadherin." (PMID 40895189, 2025). "Fibronectin and vimentin were mainly expressed in the stromal cells and also detected in cancer cells in some cases of adenocarcinoma." (PMID 40899568, 2025).
cancer (continued). "Elevated vimentin levels signify a shift toward a mesenchymal phenotype, enhancing the migratory and invasive capabilities of cancer cells." (PMID 40283503, 2025). "The cytoskeleton gets remodeled in cancer and vimentin is one of these remodeled proteins as a result of the EMT events." (PMID 40051499, 2025). "In cancer metastasis, vimentin is permanently overexpressed in cancer cells, defending them from stress and supporting cell organelles during cancer progression and EMT." (PMID 40566630, 2025). "The invasive cancer cells typically exhibit high levels of mesenchymal proteins, such as N-cadherin and vimentin." (PMID 40806251, 2025). "Further research is needed to elucidate how vimentin influences cancer biology and develop targeted therapies against it." (PMID 40229242, 2025). "In papillary TC, several mesenchymal markers, including VIM, were found to be strongly expressed in cancer cells." (PMID 41228323, 2025). "While our functional assays establish R64 as a critical determinant of vimentin filament dynamics and cancer cell migration, systematic proteomic mapping of other hypoxia‐PRMT1‐regulated methylation sites on vimentin represents an important future direction." (PMID 40884268, 2025). "Co‐treatment with 7ACC2 did not further enhance the growth inhibitory effects of ACOX1i, although a trend toward increased vimentin‐positive stromal cells was observed, suggesting fibroblast colonization of the areas vacated by dying cancer cells." (PMID 40726407, 2025). "On the contrary, morphine had an unfavourable effect on the same type of cancer, contributing to a decrease in E-cadherin and increase in vimentin, SLUG, and SNAIL levels, followed by enhanced migratory ability." (PMID 39861181, 2025). "First, they highlight extracellular vimentin as a potential biomarker for aggressive cancer phenotypes characterized by enhanced migratory capabilities and resistance to immune surveillance." (PMID 40618999, 2025). "Vimentin and Ki-67 are both cellular markers that can be used to assess cancer progression and prognosis." (PMID 40869109, 2025). "The role of vimentin in cancer extends beyond its structural function, as it is involved in regulating autophagy, intracellular signaling pathways, and protecting cells from caspase-induced proteolysis." (PMID 40666093, 2025). "We assessed the expression of two mesenchymal markers, vimentin and ß-catenin, to evaluate the mesenchymal nature as a malignant feature of cancer cells." (PMID 40361334, 2025). "In these cancer cells, VIM directly interacts with the Type I CK16, preventing FBXO21-mediated ubiquitination of CK16 and its proteasomal degradation, thus increasing CK16’s stability." (PMID 39766058, 2024). "In contrast, vimentin, an abundant cytoplasmic intermediate filament protein, is related to cancer metastasis by stabilizing cell connections." (PMID 38297301, 2024). "A more mesenchymal-like morphology, down-regulation of the epithelial marker Occludin, and increased expression of the mesenchymal markers α-SMA and Vimentin were also seen in cancer cells." (PMID 38175202, 2024). "The expression of epithelial cell marker E-cadherin and mesenchymal marker vimentin were assessed in CK+ cancer cells." (PMID 38969944, 2024). "To further identify the effects of HDAC inhibitor and PI3K inhibitor on the invasion and migration of the cancer cells, we evaluated their effect on metastasis-related protein levels, Vimentin, and E-cadherin." (PMID 38645502, 2024). "Consistent with the suppressed motility of cancer cells, the mRNA and protein expression of vimentin and snail were markedly worsened in the KO cells compared with the control cells, while the opposite result was observed for E-cadherin expression." (PMID 38297161, 2024). "Our previously reported cell surface vimentin (CSV)–targeted and membrane-anchored IL12-armed (attIL12) T cells can reduce collagen production by killing cancer-associated fibroblasts, thereby increasing T-cell infiltration." (PMID 39574893, 2024).
cancer (continued). "Expression results also showed that castration-rebound VCaP-NURR1 tumors expressed enhanced levels of phenotypic markers of EMT (reduced E-cadherin and increased vimentin levels) and cancer stemness (increased CD44 and Oct4a, and decreased CD24 levels)." (PMID 38531859, 2024). "Snail and Twist serve as the master transcription factors in regulating EMT, which drives mesenchymal phenotype and promotes cancer metastasis by upregulating genes associated with EMT, including N‐cadherin and vimentin." (PMID 39415352, 2024). "We also observed an association between 1-methylnicotinamide and the EMT state of cancer cell lines, as corroborated by the expression of VIM and CDH111." (PMID 39614072, 2024). "The data suggests that filament dynamics can be essential for vimentin filaments to bind to proteins previously known to regulate cancer." (PMID 39796712, 2024). "In contrast, co-culturing with WT macrophages upregulated the expression of vimentin and fibronectin in cancer cells, while decreasing E-cadherin expression." (PMID 39256649, 2024). "We thus propose that targeting Vimentin representing a promising therapeutic approach to limit cancer growth and spread, resulting in reduced mortality of NPC." (PMID 38191501, 2024). "Deletion of autophagy-related proteins, such as ATG4A, LC3B, and ATG12, has been associated with reduced cancer cell populations and decreased expression of vimentin, a promising marker of cancer progression." (PMID 39456967, 2024). "The EMT is a complex restructuring process that enables cancer cells to acquire a metastatic phenotype, characterized by decreased expression of E-cadherin and elevated levels of vimentin and N-cadherin." (PMID 39684626, 2024). "Since epithelial-mesenchymal transition (EMT) plays a pivotal role in aggravating metastasis and invasion of cancer cells, we assessed the expression of the epithelial marker E-Cadherin and the mesenchymal markers fibronectin and vimentin." (PMID 39487118, 2024). "Several proteins are involved in the EMT process and contribute to cancer progression and metastasis, such as Snail, Slug, and Vimentin." (PMID 38672078, 2024). "The results demonstrated that HDAC inhibitor and PI3K inhibitor significantly increased levels of E-cadherin as well as significantly decreasing levels of Vimentin in the cancer cells." (PMID 38645502, 2024). "The overexpression of mesenchymal genes, such as VIM or STC1, suggests that the MM ECs undergo EMP or endothelial–mesenchymal transition (EndMT), a process often associated with cancer progression." (PMID 39596117, 2024). "In stroma-enriched 3D model, Cytokeratin 19 and E-cadherin were expressed only by cancer cells while vimentin and fibronectin were expressed by fibroblasts." (PMID 38951897, 2024). "Taken together, these results suggest that vimentin plays a protective role against anoikis cell death, thereby potentially facilitating cancer cell metastasis." (PMID 38915055, 2024). "In the multivariable analysis for cancer detection, a positive TWIST1/Vimentin methylation were significantly linked to a heightened risk of BC." (PMID 38575639, 2024). "The expression of vimentin is a hallmark of EMT, which is known to be important for cancer cell migration and invasion." (PMID 39542246, 2024). "Outside the nucleus, peri-nuclear accumulation of vimentin filaments can drive cancer cell nuclear dysmorphia." (PMID 39542246, 2024). "As previously discussed, the process of EMT in cancer cells involves a decrease in the expression of E-cadherin and an increase in the expression of N-cadherin and Vimentin." (PMID 38350902, 2024). "Glabridin inhibits EMT by upregulating E-cadherin and downregulating EMT-related proteins like N-cadherin, Snail, and vimentin, reducing cancer cell migration and invasion." (PMID 39723390, 2024).
cancer (continued). "In most YK-1–3 cases (31 of 40 cases), only stromal cells were positive for vimentin; only a minority of cases (9 of 40 cases) showed vimentin positivity in both stroma and cancer cells." (PMID 38444414, 2024). "The success of CPMV as a platform for cancer treatment is based on two intrinsic characteristics of this virus: native tropism towards vimentin on endothelial cells and their native immunostimulatory effect within solid tumors." (PMID 38673914, 2024). "Factors such as TGF-β, HIF1α, β-catenin, IL-6, caveolin-1, vimentin, and nucleic acids, including miRNAs, which are transported with the help of exosomes secreted by cancer cells, play an important role in the mobilization of EMT regulators." (PMID 38473285, 2024). "Previous studies demonstrated PI3K/Akt pathway activation induces E-cadherin expression and inhibits vimentin expression to suppress cancer cell proliferation and migration." (PMID 38297301, 2024). "We also describe cell-surface cytokeratin and vimentin and their functions and discuss their potential as predictive biomarkers and as targets for anti-cancer therapy." (PMID 39766058, 2024). "Vimentin is a mesenchymal marker that is upregulated during EMT and is associated with increased motility and invasiveness of cancer cells." (PMID 38672078, 2024). "Cluster 25 (CD163+ApoE+) macrophages expressed S100A4 and S100A10, while Cluster 18 (ApoE+ki67+) cancer cells expressed high levels of ApoE, Ki-67, and vimentin." (PMID 39695088, 2024). "illustrated EMT responses to EGFR‐targeted chemotherapy, where treatment inhibited EMT‐driven cancer invasion by reducing vimentin levels and increasing E‐cadherin." (PMID 39101627, 2024). "These endothelial cells secrete VIM in response to pro-angiogenic signaling from the cancer cells, and angiogenesis inhibitors prevent the secretion of VIM." (PMID 39766058, 2024). "The study suggested that Gln deprivation results in the deactivation of the transcription factor ETS1, which is responsible for the expression of vimentin and metalloproteases, proteins involved in cancer cell migration and invasion." (PMID 38750263, 2024). "The Collagen-Capan-1 transplant tumors predominantly exhibited MUC1-positive ductal cancer formation, interspersed with occasional vimentin- or α-SMA-positive fibroblasts." (PMID 38612551, 2024). "Within the TCGA HGSOC cohort, GNAS expression was significantly correlated with expression of the EMT markers Vimentin and N-cadherin, and the cancer cell stemness marker PROM1." (PMID 38097740, 2024). "Nevertheless, as we shown in LUAD cells in this study, vimentin expression is often upregulated in cancer cells, in particular, in those that have undergone the EMT." (PMID 38311781, 2024). "The expression of the epithelial marker E-cadherin decreased in the cancer cells treated with shC, whereas that of the mesenchymal markers N-cadherin, Snail, Slug, and vimentin increased at the transcriptomic level." (PMID 38474121, 2024). "Cancer cell burden within the lungs at these early time points was quantified using multiplex qPCR on lung tissue for vimentin (present in all cells) and luciferase (present in cancer cells only)." (PMID 38602451, 2024). "Cancer cell migration is regulated by vimentin through the involvement of many signaling pathways, such as the AKT pathway." (PMID 39337406, 2024). "For cancer cells in culture, the addition of recombinant VIM led to an increase in invasiveness through the upregulation of Wnt signaling and β-catenin activity, which is involved in multiple critical cell signaling pathways, including EMT and proliferation." (PMID 39766058, 2024). "On the other hand, RNA-seq data showed that four other genes (DUSP6, NFIX, VIM, and SPARCL1) associated with cancer were also downregulated in CREB5 knockdown cells." (PMID 38418476, 2024). "Vimentin is a type of intermediate filament expressed in mesenchymal cells and highly invasive cancer cells." (PMID 38811770, 2024).
cancer (continued). "Many studies showed that as cancer progresses, Vimentin expression increases, while E-cadherin expression decreases." (PMID 39061649, 2024). "In vitro studies with co-cultured hepatocytes and HT29 colorectal cancer cells showed higher vimentin expression suggesting that cancer cells are able to induce EMT in hepatocytes to promote replacement growth pattern." (PMID 38255995, 2024). "Overall, this study provides insights regarding the strong correlation between vimentin expression and cancer metastasis and a basis for blocking metastasis using this novel therapeutic mechanism." (PMID 38915055, 2024). "Essential markers of EMT are crucial for enhancing migration and invasion during cancer metastasis, including the downregulation of E-cadherin and the upregulation of Vimentin." (PMID 39390599, 2024). "In contrast, the expression of the mesenchymal marker vimentin was significantly higher in cancer tissues with high FAK expression than in adjacent paracancer tissues with low FAK expression (p < 0.001)." (PMID 38560575, 2024). "After the occurrence of EMT in cancer cells, E-cadherin expression is downregulated, while proteins, such as mesenchymal markers N-cadherin, Vimentin, and Snail are upregulated." (PMID 39097833, 2024). "Sarcoma-like components in PSC express epithelial markers such as CK and EMA, while cancer cells express mesenchymal markers such as vimentin." (PMID 38968487, 2024). "Cell-surface VIM-positive cells (including cancer and immune cells) selectively bind and internalize CPMV, while cells without cell-surface VIM did not take up the virus." (PMID 39766058, 2024). "During EMT, epithelial cells transform from epithelial cells highly expressing epithelial markers (E-cadherin) to mesenchymal cells overexpressing mesenchymal markers (N-cadherin and Vimentin), which then promote the migration and invasion of cancer cells." (PMID 38713320, 2024). "Such a protrusion, which is a specialized podosome for which the newly synthesized vimentin contributes in providing a scaffold, is termed invadopodium because it is through it that cancer cells invade the stroma." (PMID 39120324, 2024). "STAT3 promotes EMT, a key factor in cancer metastasis, by reducing E-cadherin and increasing vimentin and MMP9 expression." (PMID 39519023, 2024). "The results indicate that DKK4 expressed in CRC cancer cells strongly induces the formation of Vimentin+α-SMA+ fibroblasts and α-SMA+ MYH9+ myofibroblasts in cancer stromal tissues in mouse models." (PMID 38519641, 2024). "Vimentin is a characteristic intermediate filament of mesenchymal cells with a high capacity for migration and invasion, which, in the context of cancer, would result in favoring the metastasis process and worsening the patient prognosis." (PMID 38542313, 2024). "Due to its many roles in the cell, vimentin can be studied in many disciplines, from cancer to cytoskeletal dynamics." (PMID 38389041, 2024). "We have previously reviewed the similarities between CK and VIM, especially in the context of cancer cells." (PMID 39766058, 2024). "Although these intermediate filaments have been extensively used for pathological characterization and detection of aggressive carcinomas, little is known regarding the interactions between CK and VIM when co-expressed in hybrid E/M cells." (PMID 39766058, 2024). "Regardless, the hybrid E/M cell type is pathologically critical for carcinoma progression, and the co-expression of CK and VIM in these cells is readily visible, warranting further examination and discussion." (PMID 39766058, 2024). "In this study, we demonstrated that Trametinib, a MEK1/2 signaling cascade inhibitor that is clinically employed to treat carcinoma, holds great potential as a laboratory chemical for remodeling cytoskeletal vimentin network in living cells." (PMID 38429984, 2024).